SMAD4 (SMAD family member 4)
Diseases named in the same sentence as SMAD4 in open-access papers (continued):
Sharing a sentence is not in itself a finding about the gene and the disease.
thyroid cancer (10 papers, 2012 to 2025). "Loss-of-function somatic alterations of the SMAD4 gene have been linked to a wide range of tumor types, including pancreatic, colorectal, gastric, breast, and thyroid cancer, and germline genetic alterations, which have been associated with JPS." (PMID 39063183, 2024). "All this leads to the assumption that the presence of SMAD4 mutations cannot differentiate between well-differentiated thyroid cancer and PDTC." (PMID 29133385, 2018). "SMAD4 mutations are involved in the pathogenesis of JP, and it has been shown that mutations in this gene also contribute to tumour progression in thyroid cancer." (PMID 30251589, 2018). "Differences in immune cell count between benign and malignant thyroid tumors were also associated with distinction in STAT6 and SMAD4 expression." (PMID 39936166, 2025). "An in-depth examination of SMAD4 status demonstrated that abnormalities in this locus occur in benign as well as in malignant thyroid tumours (15/56, 27%), which was interpreted by the authors as indicative of an early event in thyroid tumorigenesis." (PMID 29133385, 2018). "In thyroid cancer, miR-146b-5p was highly expressed and inhibited Smad4 gene expression, which favored the resistance of tumors to a TGF-β inhibitory signal." (PMID 27941605, 2016). "Some studies have reported a frequent overexpression of Smad-4 and Smad-7 in thyroid cancer." (PMID 37905271, 2023). "Similarly, the lncRNA CATIP-AS1 modulates EMT in thyroid cancer cells through a regulatory axis involving miR-515-5p and the TGF-β signaling mediator Smad4." (PMID 41154428, 2025).
cyst (9 papers, 2017 to 2023). A sac-like closed membranous structure that may be empty or contain fluid or amorphous material. "Additional genes provided a marginal improvement in sensitivity but were associated with cyst type (e.g. VHL) and grade (e.g. SMAD4)." (PMID 31258847, 2019). "In this study, to investigate the function of BMP in intestinal stromal cells, we disrupted BMP signaling in Gli1+ stromal cells by ablating Alk3 and Smad4 and found that the large intestine showed abnormal morphology, accompanied with severe diarrhea and cyst-like polypus." (PMID 37889976, 2023). "GS4 mice also developed cyst-like polypus in 60 days after Smad4 knockout (KO)." (PMID 37889976, 2023).
gastric polyps (9 papers, 2008 to 2024). "Patients with SMAD4 mutations are reported to experience a higher prevalence of gastric polyps and twice the frequency of anemia as that of patients with BMPR1A mutations." (PMID 35928693, 2022). "Only two participants (15%) had gastric involvement without colonic involvement (one with the BMPR1A Bukharin mutation and the other one with SMAD4), and all five participants with SB involvement had colonic involvement as well (four of them had also gastric polyps)." (PMID 35057835, 2022). "Gastric polyps are significantly less common inBMPR1a DCV carriers than SMAD4 DCV carriers (8% vs 73%, p < 0.001, and 13% vs 39%, p = 0.001)." (PMID 37400896, 2023). "MD has been diagnosed concurrently in SMAD4 + JPS patients with gastric polyposis, marked by giant mucosal folds in gastric fundus and body, with diminished acid secretory capacity and protein losing state causing hypoalbuminemia." (PMID 38066625, 2023). "Of those with upper GI involvement, 13(92%) had gastric polyps (five patients had the BMPR1A Bukharin mutation and four had SMAD4 mutation)." (PMID 35057835, 2022). "SMAD4 (DPC4) knockout mice develop multiple duodenal and gastric polyps that demonstrate considerable similarity to those found in human JPS, including moderate stromal cell proliferation and infiltration by plasma cells and eosinophils." (PMID 26049720, 2015). "Genotypic and phenotypic correlations have generally been poor with these gene mutations but a recent report has shown a strong correlation between massive gastric polyposis and the presence of a SMAD4 gene mutation versus the BMPR1A or no mutation." (PMID 18826596, 2008). "Unlike in SMAD4 carriers, gastric polyposis and malignancy were not identified in our review in BMPR1a carriers, but colonic polyposis and malignancy occurred in carriers of either BMPR1a or SMAD4 DCVs." (PMID 37400896, 2023). "BMPR1a DCV carriers do not display massive gastric polyposis (> 100 gastric polyps), with 86% of BMPR1a DCV carriers having < 5 gastric polyps, whereas 17% of SMAD4 DCV carriers had > 100 gastric polyps (p = 0.0001)." (PMID 37400896, 2023).
juvenile polyp (9 papers, 2013 to 2024). A non-neoplastic hamartomatous polyp that arises from the stomach and intestinal tract. "The detection of hamartomatous juvenile polyps along with an inflammatory, edematous, and erythematous appearance of the gastric mucosa should lead to a suspicion of SMAD4-related JPS." (PMID 39039610, 2024). "In a recent study two SMAD4 mutations in patients without juvenile polyps were identified, one with around 20–99 adenomatous polyps and the other one without reported polyps, which further extends the phenotypical spectrum for this gene." (PMID 27696107, 2017). "The various gene defects associated with juvenile polyps are LKB1, PTEN, SMAD4, and so forth." (PMID 23970988, 2013). "All patients with a PV in SMAD4 or BMPR1A had polyps removed and, furthermore, in approximately 15% of the patients no juvenile polyps (but other types) had been removed." (PMID 37354305, 2023).
Myocardial fibrosis (9 papers, 2020 to 2025). "In human cardiac fibroblasts, miR-452-5p was confirmed to target SMAD4, thereby influencing myocardial fibrosis." (PMID 40149647, 2025). "In vitro studies have confirmed that miR-34a plays a significant role in the progression of myocardial fibrosis by directly targeting Smad4." (PMID 39250437, 2024). "In vivo and in vitro studies have demonstrated that miR-34a promotes myocardial fibrosis in mice after myocardial infarction (MI) by targeting mothers against decapentaplegic homolog 4 (Smad4)." (PMID 39250437, 2024). "Smad4 signaling can induce the apoptosis in cardiomyocytes and specific deletion of Smad4 in cardiomyocytes leads to cardiac hypertrophy, aggravating the myocardial fibrosis." (PMID 36843918, 2023). "MiR-1305 and miR-587 were found to regulate the expression of TGF-β pathway members related to virus infections and lymphocytes T activation, Mothers Against DPP Family Members - SMAD3, and SMAD4), ventricular remodeling, myocardial fibrosis and hypertrophy and, as a result, HF progression." (PMID 33233425, 2020). "Improved cardiac function and reduced myocardial fibrosis are noted in animals treated with cardiosphere-derived cell-secreted exosomes depending on miR-146a-5p decreases the expression of TRAF6, Smad4, and FOS." (PMID 40492132, 2025).
osteoporosis (9 papers, 2017 to 2024). A condition of reduced bone mass, with decreased cortical thickness and a decrease in the number and size of the trabeculae of cancellous bone (but normal chemical composition), resulting in increased fracture incidence. "Forming a complex with SMAD4, it translocates into the nucleus to activate RUNX2, which is associated with PTH and osteoporosis." (PMID 36011354, 2022). "Enhancing osteoblast or osteocyte viability sets the stage for protection against osteoporosis, ie SMAD4 is essential for recovery from pathological bone conditions." (PMID 34841647, 2022). "Further clinical analysis of miR-146a-Smad4 in patients with osteoporosis should demonstrate the clinical relevance of the current study and thus shed light on osteoporosis prevention and therapy." (PMID 29167750, 2017). "The upregulation of miR‐146a decreases the SMAD4 expression in osteoporosis patients." (PMID 34841647, 2022). "Riveting on our findings, up‐regulation of miR‐497 or down‐regulation of LRG1 could activate TGF‐β signalling pathway as accompanied by increased TGF‐β1, Smad3, Smad4 and p‐Smad2/3 protein expression and reduced Smad7 protein expression in osteoporosis." (PMID 32975015, 2020). "Increased miR-146a expression in turn inhibits osteogenesis, thus at least partially explaining how inflammation augments osteoporosis. miR-146a decreases osteogenic differentiation by post-transcriptionally downregulating Smad4, an essential mediator of the BMP pathway." (PMID 29167750, 2017). "Thus, further clarification of the status of the miR-146a-Smad4 axis in clinical osteoporosis patients or in an ovariectomized mouse model would shed light on targeting this axis as a potential therapeutic strategy." (PMID 29167750, 2017). "Promotion of Smad4 expression may be an important approach for the treatment of osteoporosis." (PMID 34692253, 2021). "The results showed that miR-183 was upregulated in osteoporosis, and miR-183 overexpression inhibited osteoblast differentiation by deliberately downregulating the TGF-β–Smad4 pathway member to induce osteoporosis." (PMID 38892426, 2024).
prostate tumor (9 papers, 2013 to 2025). "Proliferation markers (MKI67 and PCNA) were highly expressed in prostate tumor tissue of Pten/Smad4 KO mice but barely detected in prostate tissue of Pten/Smad4/Kmt9α KO and Ctrl mice." (PMID 39885202, 2025). "In Pten/Smad4 KO mice, we observed large prostate tumors while prostates of Ctrl and Pten/Smad4/Kmt9α KO mice appeared normal." (PMID 39885202, 2025). "On the other hand, mRNA levels of ROR2, NFKBIA, DUSP6, PLCB3, and SMAD4 are lower in metastatic prostate tumors as compared to primary prostate tumors." (PMID 27191743, 2016). "The coordinated roles of several factors including Nkx3.1, cMyc, β-catenin, phosphatase and tensin homolog, and Smad4 contribute to prostatic tumor progression (43, 61, –, 64)." (PMID 24731097, 2014). "Advanced primary prostate tumors often metastasize to the bone, potentially reflecting parallel events whereby bone-derived TGF-β offers an advantage to SMAD4-overexpressing prostate tumor cells and providing a possible therapeutic target in the TGF-β pathway." (PMID 24708576, 2014). "Furthermore, SMAD3 and SMAD4 were also downregulated in human prostate tumors being positive for ETV1 gene fusions." (PMID 31160676, 2019). "Compared to the primary prostate tumors, mRNA level of NFKBIA, DUSP6, PLCB3, and SMAD4 are lower in metastatic prostate tumors, while mRNA level of RELA and SNAI1 exhibit opposite trend." (PMID 27191743, 2016).
renal cell carcinoma (9 papers, 2006 to 2025). "In addition, miR-1260b, highly expressed in renal cell carcinoma, promoted cellular proliferation and invasion via the reduction of the expression of several tumor suppressor genes associated with Wnt signaling, such as sFRP1, Smad4, and Dkk263." (PMID 32523124, 2020). "A previous report indicates that miR-452-5p abrogate posttranscriptional SMAD4 activity in human renal cell carcinoma cell lines." (PMID 38883840, 2024).
stomach cancer (9 papers, 2013 to 2024). "Interestingly, T-cell specific deletion of Smad4 induces gastric tumors, as well as colon, duodenal and oral cavity tumors, with induction of inflammatory cytokines." (PMID 24216700, 2013). "Heterozygous Smad4 knockout mice (mixed C57BL/6 × Sv/129 background and C57BL/6 background) exhibited spontaneous gastric tumor development." (PMID 24216700, 2013).
anemia (8 papers, 2016 to 2025). A reduction in the number of red blood cells, the amount of hemoglobin, and/or the volume of packed red blood cells. "Cases 2 and 3 presented with anemia, which is consistent with the high prevalence of anemia in patients with SMAD4 mutations." (PMID 35928693, 2022). "However, children with an SMAD4 mutation should be considered at risk for earlier GI bleeding and secondary anemia." (PMID 32842615, 2020). "To investigate whether increased Smad4 level and iron deposition in the duodenum of anemic piglets could influence Hif-2α–dependent transcriptional response of genes responsible for iron absorption during anemia, we checked mRNA expression of particular genes." (PMID 33396831, 2020). "In the duodenum of anemic piglets, despite systemic anemia, increased ferritin expression and iron deposition within duodenal villi clearly denote iron accumulation, leading to the increased Smad4 expression, which in turn may result in reducing Hif-2α transcriptional activity." (PMID 33396831, 2020).
arteriovenous malformations (8 papers, 2013 to 2025). "This study elucidates distinct molecular and mechanistic pathways underlying arteriovenous malformation (AVM) formation in endothelial cells (ECs) with SMAD4 and Alk1 loss-of-function (LOF)." (PMID 39829872, 2025). "We observed numerous arteriovenous malformations (AVMs) in the retinas of Smad4 mutants, similar to those identified in Alk1- and Eng-deficient mice." (PMID 29460088, 2018). "Importantly, those with JPS caused by BMPR1a DCVs do not display any features of HHT (epistaxis, telangiectasia and arteriovenous malformations) as seen in SMAD4 DCV carriers." (PMID 37400896, 2023). "Because RASA1 mutations have previously been associated with capillary and arteriovenous malformations similar to the HHT phenotype, and because no variants were identified in the ENG, ACVRL1, or SMAD4 genes, the RASA1 variant was assumed to be the causative mutation for this sample." (PMID 24268183, 2013).
cardiac hypertrophy (8 papers, 2012 to 2023). "For the first time, the result provides in vivo genetic evidence demonstrating that the endogenous cardiomyocyte Smad4-dependent TGF-β pathway protects heart from cardiac hypertrophy and fibrosis." (PMID 22926414, 2012). "We would prove that H19 suppresses cardiac hypertrophy through the MicroRNA-145-3p/SMAD4 axis." (PMID 35139769, 2022). "Moreover, mice with knockout of Smad4—a mediator of Smad2/3 nuclear translocation—develop cardiac hypertrophy, whereas overexpression of Smad2 attenuates cardiomyocyte hypertrophy." (PMID 29783655, 2018). "Interestingly, the depletion of SMAD4 in cardiomyocytes contributes to cardiac hypertrophy." (PMID 35139769, 2022). "Additionally, ablation of Smad4 in mice generates cardiac hypertrophy and heart failure." (PMID 29783655, 2018). "We have previously shown that targeted deletion of Smad4, the central intracellular mediator of TGF-β superfamily signaling, in cardiomyocyte, unexpectedly leads to cardiac hypertrophy." (PMID 22926414, 2012). "The results of the current study are consistent with the notion that cardiac hypertrophy is preceded by sharp upregulation in the mRNA expression levels of profibrotic markers (TGF-β, SMAD-2, SMAD-3, SMAD-4, and NF-κβ) and marked downregulation of antifibrotic SMAD-7 mRNA and let-7b miRNA." (PMID 36030321, 2022).
colorectal polyps (8 papers, 2015 to 2025). "It has been shown that mice with SMAD4 deletion or loss of SMAD4-dependent signaling have increased susceptibility to developing colorectal polyp and cancer." (PMID 35154600, 2021). "In this study, 39 and 30 fresh tissue specimens for colorectal polyp and intestinal-type adenocarcinoma, respectively, and adjacent normal tissue were examined for the desired sequences of the SMAD4 gene." (PMID 35154600, 2021). "Colonic polyps are seen in both carriers of BMPR1a and SMAD4 DCVs, however SMAD4 DCV carriers have higher colorectal polyp numbers than BMPR1a DCV carriers." (PMID 37400896, 2023). "A gene-phenotype association, which relates the genotypic differences seen in these patients to the phenotype they display, has been defined, as colorectal polyps are seen in those with either a BMPR1a or SMAD4 DCV, but gastric and upper GI polyps are not commonly seen in those with a BMPR1a DCV." (PMID 37400896, 2023).
dysplasia (8 papers, 2013 to 2024). A usually neoplastic transformation of the cell, associated with altered architectural tissue patterns. "SMAD4 mutations are often associated with multiple polyposis of the stomach, which causes severe bleeding and hypoproteinemia; severe dysplasia and adenocarcinoma are observed in rare cases." (PMID 38191939, 2024). "Skeletal dysplasia due to Smad4 deficiency resembles other skeletal dysplasias resulting from mutations in polarity pathways, such as the Ror2/Wnt5a PCP pathway with Robinow syndrome and brachydactyly B2." (PMID 28167493, 2017). "We found that loss of Smad4 specifically on surface lens ectoderm leads to microphthalmia and dysplasia of retina." (PMID 27494603, 2016). "SMAD4 mutations are frequently associated with multiple polyposis of the stomach; the condition causes severe bleeding and hypoproteinemia, which may progress to severe dysplasia and adenocarcinoma formation." (PMID 38191939, 2024). "Kaplan-Meier analysis revealed that the combination of SMAD4 expression and histological grade of dysplasia (p = 0.007) is a better predictor for the malignant transformation of oral leukoplakia." (PMID 23826135, 2013). "Furthermore, SMAD4 expression was significantly reduced in all stages of Barrett’s oesophagus from chemotaxis to hypo- and highly heterogeneous hyperplasia, and knockdown of SMAD4 was sufficient to promote tumourigenesis in dysplastic Barrett’s oesophagus cells in vivo." (PMID 37685308, 2023). "Across dysplasia samples, multiple oncogenic drivers were seen, including APC, KRAS, and SMAD4 mutations, with no alterations clearly emerging in the transition to carcinoma." (PMID 36611031, 2023). "Their analysis of a 332-tissue microarray, which was performed along the normal epithelium-atrophic gastritis-dysplasia-carcinoma sequence, showed that TGF-β1 and TβR1 expression continually increased along this sequence, while Smad 2/3 and Smad4 decreased as carcinoma progressed." (PMID 26846663, 2016).
esophageal squamous cell carcinoma (8 papers, 2010 to 2025). Esophageal squamous cell carcinoma (ESCC) is a type of esophageal carcinoma (EC) that can affect any part of the esophagus, but is usually located in the upper or middle third. "In human esophageal SCC, 51.2% ~ 67.8% patients showed Smad4 loss or reduction and Smad4 loss is associated with invasion of esophageal SCC." (PMID 22204491, 2011). "SMAD4 is enriched in adherens junction and cell cycle pathways and has been found to have a potential predictive value for esophageal squamous cell carcinoma in patients receiving neoadjuvant chemoradiotherapy RBL2 and CDKN1B are enhanced in cell cycle pathways." (PMID 24604236, 2014).